HLA-G (major histocompatibility complex, class I, G)
Diseases named in the same sentence as HLA-G in open-access papers (continued):
Sharing a sentence is not in itself a finding about the gene and the disease.
psoriasis (8 papers, 2014 to 2023). An autoimmune condition characterized by red, well-delineated plaques with silvery scales that are usually on the extensor surfaces and scalp. "For example, HLA-G*01:06:01 showed a strong association with psoriasis (OR: 1.80, 95% CI: 1.70–1.90, p: 3.57 × 10−100, EAF: 6.2%)." (PMID 37923823, 2023). "Interestingly, significantly lower plasma sHLA-G levels have been found in psoriatic patients compared with controls, suggesting a difference in systemic HLA-G expression that could be associated with the IL-10 deficiency typical of psoriasis." (PMID 25477881, 2014). "HLA-G was detected in psoriasis, mainly in the macrophages of the dermo-epidermal junction." (PMID 34201301, 2021). "In line with the possible presence of a dysregulation of innate immune receptors for self in PsA, low plasma levels of soluble HLA-G, the high-affinity ligand for ILT4, were found in patients with psoriasis compared to healthy controls." (PMID 24676037, 2014).
Allergy (7 papers, 2010 to 2025). An allergy is an immune response or reaction to substances that are usually not harmful. "In transplantation, HLA-G molecule has been shown to be important for a better allograft acceptance, whereas low serum levels seem to increase the risk of autoimmunity and allergy." (PMID 26862036, 2016). "HLA-G molecules, both in membrane-bound and in soluble forms, are known to play a key immunoregulatory role and their involvement in allergic diseases is supported by increasing literature data." (PMID 35082780, 2021). "In patients that experience an allergic reaction, HLA-G expression as well as sHLA-G secretion are increased in CD4+ cells and monocytes after in vitro stimulation by the causal allergen, but not by non-specific stimuli and non-causal allergens." (PMID 32983083, 2020). "Soluble HLA-G has already been proposed as predictor of in vitro fecundation outcome, but also as biomarker of allergy, allograft and cancers." (PMID 26862036, 2016). "In this review, we discuss the current knowledge and the potential role of HLA-G in allergic diseases." (PMID 27413762, 2016). "Moreover, it has been reported that in infants with soluble HLA-G, plasma levels were significantly higher in subjects with persistent wheezing compared with subjects with transient wheezing; thus, HLA-G is a promising biomarker in allergies or other diseases." (PMID 40573358, 2025). "In conclusion, it could be postulated that HLA-G molecules in allergy may be either compensatory or pathogenetic, but their precise mechanism of action is not yet completely known and needs further investigation." (PMID 35082780, 2021). "At present, it is difficult to completely clarify the role of HLA-G in allergic diseases." (PMID 27413762, 2016). "Although at present is difficult to completely define the role of HLA-G molecules in allergic diseases, it may be suggested that they are specifically expressed and secreted by immune cells during the allergic reaction in an attempt to suppress allergic inflammation." (PMID 35082780, 2021). "Collectively, although at present it is difficult to completely define the role of HLA-G molecules in allergic diseases, it may be suggested that they are expressed and secreted by immune cells during the allergic reaction in an attempt to suppress allergic inflammation." (PMID 27413762, 2016). "The relationship among allergy, infections and HLA-G is an intriguing question, however no data are currently available on this topic." (PMID 35082780, 2021).
bladder cancer (7 papers, 2018 to 2024). "In bladder cancer (BC) tumors, the association of HLA-G with cancer progression has to be explained." (PMID 39594832, 2024). "The expression of HLA-G in bladder cancer strongly correlates with tumor aggressiveness and poor survival outcomes." (PMID 38542078, 2024). "Human leukocyte antigen G (HLA-G) is an immunosuppressive molecule that is often found at higher levels in various cancers, including bladder cancer (BC)." (PMID 39594832, 2024). "FGF4 gene showed a hazard ratio (HR) = 8.21 (95% CI, 1.13–9.58) and logrank p-value = 0.012 for bladder carcinoma indicating that the result was statistically significant (the relation between the high expression of the HLA-G gene and more survival rate)." (PMID 35888106, 2022). "HLA-G is frequently but heterogeneously expressed in various cancers, including bladder cancer." (PMID 38542078, 2024). "However, there was a highly significant increase in the expression of HLA-G in bladder cancer cases with metastatic prostate infiltration." (PMID 39594832, 2024). "Furthermore, higher levels of HLA-G transcripts than HLA-G protein were found in bladder cancer suggesting a posttranscriptional control comparable to that of RCC lesions." (PMID 35185904, 2022). "HLA-G is an immune checkpoint molecule well known for its tolerogenic role in maternal-fetal tolerance, and that is commonly neo-expressed by solid tumors (including bladder cancer)." (PMID 30237859, 2018). "Thus, blocking HLA-G/ILT2-related PD-1/PD-L1 interactions might be an effective treatment strategy for bladder cancer." (PMID 38542078, 2024). "However, HLA-G-regulating mRNAs have not been yet investigated in bladder cancer." (PMID 35185904, 2022).
celiac disease (7 papers, 2015 to 2023). An autoimmune genetic disorder with an unknown pattern of inheritance that primarily affects the digestive tract. "For example, HLA-G*01:01:02 was associated with a 0.70-fold decrease in odds of coeliac disease (95% CI: 0.65–0.75, p: 1.72 × 10−20), while the burden test of its dummy 3-field allele showed an opposite direction (OR: 1.29, 95% CI: 1.21–1.39, p: 7.98 × 10−13)." (PMID 37923823, 2023). "This suggests that at least one synonymous variant in HLA-G*01:01 obviates the association of HLA-G*01:01:02 with coeliac disease." (PMID 37923823, 2023). "Data from genetic analyses of patients with celiac disease showed that there are characteristic polymorphisms of the HLA-G gene, which indicate an increased susceptibility to the disease in these people." (PMID 34948145, 2021).
choriocarcinoma (7 papers, 2008 to 2022). An aggressive malignant tumor arising from trophoblastic cells. "Studies have found that high expression of human leukocyte antigen-G (HLA-G) is a strong candidate gene for predicting the resistance of choriocarcinoma to MTX single-agent chemotherapy." (PMID 36439425, 2022). "In choriocarcinoma, HLA-G is demonstrated to change the tumor microenvironment through the inactivation of the local immune system at very high levels and functions." (PMID 35409376, 2022). "Untreated JEG-3 cells, a choriocarcinoma cell line, was included as a positive control for HLA-G expression during visualization of the flow cytometry results." (PMID 32560316, 2020). "It has been reported that the CpG islands in the HLA-G promoter region of JAR (choriocarcinoma) cells, which does not express HLA-G, were fully methylated, whereas for an HLA-G expressing cell such as JEG-3, the CpG islands were only partially methylated." (PMID 24741620, 2014).
malaria (7 papers, 2014 to 2025). Malaria is a serious and sometimes fatal disease caused by a parasite that commonly infects a certain type of mosquito which feeds on humans. "Overall, we observed that among the iron-fortified children, HLA-G 14 bp + /- and 14 bp-/- variants were associated with a higher likelihood of developing severe malaria." (PMID 40953010, 2025). "This study revealed that people who carry the HLA-G 14 bp insertion/deletion polymorphism are more susceptible to severe malaria, which increases their vulnerability to anaemia." (PMID 40953010, 2025). "The results of this study underline the importance of HLA-G 14 bp + /- variant screening before any iron supplements in children in malaria-endemic areas." (PMID 40953010, 2025). "The research findings indicate that among the iron-fortified children with HLA-G, 14 bp + /- and 14 bp-/- variants are likely to develop severe malaria." (PMID 40953010, 2025). "Similar studies also found that HLA-G 14 bp variants were linked to increased severe malaria risk and higher anaemia odds in iron-supplemented children, highlighting genetic influences on health outcomes." (PMID 40953010, 2025). "The association between HLA-G and the risk of malaria has been shown recently by our team at genetic and protein levels." (PMID 31235762, 2019). "Recent studies have shown an association between the risk of malaria and HLA-G at both genetic and protein levels." (PMID 31235762, 2019). "A first study conducted in Benin has shown that the production of soluble HLA-G (sHLA-G) during the first months of life is strongly correlated with the maternal level at delivery and associated with low birth weight and malaria." (PMID 28166246, 2017). "Due to the important role of HLA-G in immune regulation and immune tolerance and to its strong expression during pregnancy, the potential association between sHLA-G during the whole pregnancy, and not only at delivery and malaria needs to be explored." (PMID 28166246, 2017). "Overall, the results underline the complexity of the association between HLA-G and malaria and need further experimental exploration." (PMID 28166246, 2017). "This approach permitted us to explore more precisely the complex association between malaria and HLA-G." (PMID 26862036, 2016). "Its role during infections is discussed, and it has been described that high levels of soluble HLA-G during childhood increase the risk of malaria." (PMID 26862036, 2016). "In all groups, low birth weight, high number of malaria infections and high exposure to malaria transmission were associated with high level of soluble HLA-G." (PMID 26862036, 2016). "This study is the first to investigate the association of soluble HLA-G and malaria in pregnant women and newborns." (PMID 25115633, 2014). "Therefore, we aimed to evaluate the effect of HLA-G 14 bp polymorphism and its associated risk of malaria severity among Ghanaian infants and young children on iron fortification." (PMID 40953010, 2025). "Conducting HLA-G 14 bp polymorphism screening prior to commencing iron supplementation may effectively identify children at increased risk for severe malaria complications." (PMID 40953010, 2025). "In addition, antibody responses to protective vaccine candidates for malaria are dependent on polymorphisms in the HLA-G gene." (PMID 35204759, 2022). "Hence, in malaria, increased levels of HLA-G in infected mothers are associated with an increased risk to acquire malaria during infancy." (PMID 31474955, 2019). "However, the direct association between the mothers’ levels of soluble HLA-G and the risk of malaria for their newborns remained unexplored." (PMID 31235762, 2019). "A genetic association between HLA-G and malaria has already been pointed out." (PMID 26862036, 2016). "Soluble HLA-G may represent a useful marker of susceptibility to malaria in infants and be associated with the higher susceptibility to infection observed for LBW children." (PMID 25115633, 2014).
malaria (continued). "A recent work reported that high levels of sHLA-G were significantly associated with a higher incidence ratio of malaria in Beninese children consistent with the fact that the inhibition of immune responses by HLA-G expression could lead to a greater susceptibility to malaria." (PMID 26862036, 2016). "The 14 bp deletion of HLA-G in malaria correlates with elevated circulating amounts of soluble HLA-G, which has significant immunosuppressive capabilities via interacting with inhibitory receptors on immune cells." (PMID 40953010, 2025). "Several studies have reported that, regarding malaria, the role of HLA-G has drawn significant interest due to its immunomodulatory properties." (PMID 40953010, 2025). "Future studies should explore the molecular pathways via which HLA-G variations regulate immunological responses to malaria in iron-supplemented people." (PMID 40953010, 2025). "The finding that iron-fortified infants with the HLA-G 14 bp + /- and 14 bp-/- variations showed increased vulnerability to severe malaria indicates the potential need for tailored dietary therapy." (PMID 40953010, 2025). "The expression of HLA-G gene and molecule has been also investigated in protozoan parasitic diseases including African trypanosomiasis, Chagas disease, malaria, toxoplasmosis, and leishmaniasis." (PMID 35204759, 2022). "It is still unknown if variations in the HLA-G 14 bp gene among Ghanaian children receiving iron supplementation could influence malaria disease outcome and severity." (PMID 40953010, 2025). "During the multivariate analysis, both environmental exposure to malaria (aHR = 1.3, 95%CI [1.11–1.48], p < 10−3) and s-HLAG at ANV1, used as quantitative variable, (aHR = 1.02, 95%CI [1.01–1.03], p = 0.01) remained significantly associated with the risk of first infection." (PMID 31235762, 2019). "To date, only three studies have explored the relationship between HLA-G and malaria." (PMID 25115633, 2014). "Therefore, the impact of HLA-G on NK cell functions should be considered at two levels since it may have a role in immune responses against malaria but also in vascularization processes induced during pregnancy." (PMID 28166246, 2017). "Thus, the main objective of the present work was to explore the existence and characteristics of groups of children with different patterns of soluble HLA-G evolution between birth and 12 months of life in a cohort of Beninese children exposed to malaria, using latent class analysis." (PMID 26862036, 2016). "However under-detection of malaria events is unlikely to be related to the maternal HLA-G level and this should not constitute a major and particularly specific bias in the results." (PMID 31235762, 2019).
acute myeloid leukemia (6 papers, 2014 to 2024). Acute myeloid leukemia (AML) is a group of neoplasms arising from precursor cells committed to the myeloid cell-line differentiation. "Recently, it has been shown that aNK cells with single-KIR+NKG2C+ expanded from selected HCMV infected donors with feeder cells loaded with HLA-G leader-derived peptides have potent reactivity towards HLA-mismatched acute myeloid leukemia cells." (PMID 37809084, 2023). "However, the role of HLA-G expression and functions in Acute Myeloid Leukemia (AML) is still controversial." (PMID 24741612, 2014).
esophageal squamous cell carcinoma (6 papers, 2016 to 2024). Esophageal squamous cell carcinoma (ESCC) is a type of esophageal carcinoma (EC) that can affect any part of the esophagus, but is usually located in the upper or middle third. "Percentage of HLA-G expression in different blocks of esophageal squamous cell carcinoma." (PMID 33329527, 2020). "Three studies reported on the correlation between tumour HLA-G expression and clinical outcome of esophageal squamous cell carcinoma (ESCC) patients." (PMID 34361031, 2021).
gastric adenocarcinoma (6 papers, 2020 to 2024). "Such an approach will allow us to assess the suitability of HLA-G variants as potential risk markers for gastric adenocarcinoma and elucidate their significance in the prognosis of this type of cancer." (PMID 39549048, 2024). "Taking all these findings together, we put forward a clear association between the presence of HLA-G*01:01:01 and the development of gastric adenocarcinoma." (PMID 39408976, 2024). "In this study, we examined HLA-G 3’UTR polymorphisms in paired tissue samples from 111 patients with gastric adenocarcinoma and 119 healthy controls." (PMID 39549048, 2024). "This approach will allow us to determine whether the HLA-G variants may be adequate gastric adenocarcinoma risk markers and whether somatic mutations take place in tumoral, but not healthy, gastric tissue." (PMID 34557189, 2021). "The increase in the frequency of DEL/C haplotype matches the results obtained in the analysis of the individual polymorphisms, suggesting that both 14bp DEL and +3142C variants (that presumably lead to a higher HLA-G expression)are associated with susceptibility to gastric adenocarcinoma." (PMID 34557189, 2021). "In conclusion, the variants predominant in patients were those increasing HLA-G mRNA stability and HLA-G expression, clearly involving this molecule in gastric adenocarcinoma susceptibility, disease progression and survival and making it a potential target for immunotherapeutic approaches." (PMID 34557189, 2021). "In the present study, we studied the polymorphism of HLA-G genes in a cohort of Spanish gastric adenocarcinoma patients, to determine whether variations in the HLA-G gene were associated with genetic risks or protective factors influencing cancer progression and survival." (PMID 39408976, 2024). "In the present paper, we compare the HLA-G profile of our gastric adenocarcinoma cohort with that of a healthy Spanish cohort previously published." (PMID 39408976, 2024). "This is the first study that has reported the HLA-G allelic profile of Spanish patients with gastric adenocarcinoma." (PMID 39408976, 2024). "A higher frequency of the variants increasing HLA-G mRNA stability (14bp DEL and +3142 C) is expected in patients, as they will favor the development and progression of gastric adenocarcinoma." (PMID 34557189, 2021). "We thus decided to analyze the involvement of HLA-G in the development of gastric adenocarcinoma." (PMID 34557189, 2021).
Gestational Diabetes Mellitus (6 papers, 2016 to 2025). "In different studies in regard to gestational diabetes and the role of HLA-G immune tolerance molecule, recommendations have been made, but so far, a study which directly deals with this molecule in gestational diabetes has not been carried out." (PMID 27757202, 2016). "The results of this study showed significant reduction of HLA-G levels in pregnant women with gestational diabetes compared with normal pregnant women." (PMID 27757202, 2016). "Soluble HLA-G levels decreased in pregnant women with gestational diabetes compared with control group." (PMID 27757202, 2016). "In this study, we found that HLA-G levels were reduced in women with gestational diabetes compared with control group." (PMID 27757202, 2016). "In this case-control study, we measured serum HLA-G levels in 24 pregnant women with gestational diabetes compared with 30 normal pregnant women using sandwich ELISA." (PMID 27757202, 2016). "HLA-G levels were significantly low in pregnant women with gestational diabetes in contrast to normal pregnant women (P=0.001)." (PMID 27757202, 2016). "Moreover, two UTR variants (rs1063320 and rs6296) in HLA-G and HTR1B were associated with the risk of T2D in the studied population, and studies have also identified the association of HLA-G in the risk of gestational diabetes mellitus and type 1 diabetes." (PMID 39747296, 2025). "We tested the hypothesis that HLA-G expression is altered in placentas of women with gestational diabetes mellitus (GDM) in a specific pattern that depends on fetal sex." (PMID 36538164, 2023). "Therefore, in this study, the role of soluble HLA-G in women with gestational diabetes compared with healthy controls was studied." (PMID 27757202, 2016). "So we can conclude that HLA-G molecule is among the factors for regulation and control of the immune response and the induction of tolerance and can be an important indicator in determining gestational diabetes." (PMID 27757202, 2016). "Therefore, it is recommended that HLA-G in pregnant women is tested as an effective molecule so as to take an important step in the prediction of gestational diabetes to prevent problems and consequences of this disease." (PMID 27757202, 2016). "Therefore, it is suggested that measurement of HLA-G in pregnant women can be considered as an indicator in prognosis of gestational diabetes." (PMID 27757202, 2016).